ENSG00000304313 (novel transcript)
Gene: Long non-coding RNA gene on chromosome 21 (29,178,096 to 29,182,343, forward strand). Ensembl gene ENSG00000304313.
Gene Ontology:
Biological process: RNA processing
Cellular component: nucleolus